IGF1R (insulin like growth factor 1 receptor)
Diseases named in the same sentence as IGF1R in open-access papers (continued):
Sharing a sentence is not in itself a finding about the gene and the disease.
cancer (continued). "Our previous findings revealed a subpopulation of cancer cells that displayed a distinct “cancer stem-like” phenotype with an altered chromatin state, and increased sensitivity to an IGF-1R TKI and HDAC inhibitors." (PMID 25193862, 2014). "IGF-1R expression is critical for anchorage-independent growth, a well identified property of cancer cells." (PMID 25424625, 2014). "Abnormal activation of IGF-1R/mTOR signaling has been frequently observed in a variety of cancers including HCC." (PMID 25026290, 2014). "Currently more than 100 clinical studies examining a variety of anti-IGF1R agents in several cancer entities are ongoing." (PMID 24809298, 2014). "In cancer cells, IGF-1R activates IRS-1 by stimulating several intracellular signaling proteins such as PI3K and Akt kinase." (PMID 24970012, 2014). "The type 1 insulin-like growth factor receptor (IGF-1R) is a promising target for cancer therapy with antibodies and small molecule tyrosine kinase inhibitors (TKIs) which have been actively tested clinically." (PMID 24970814, 2014). "Upregulation of miR-497 inhibited proliferation, enhanced apoptosis and promoted sensitivity to gemcitabine through directly downregulating IGF-1R expression in PDAC cancer cells in vitro." (PMID 24667580, 2014). "In this study, we showed that glucosamine effectively inhibits IGF-1R-mediated Akt signal transduction in various human carcinoma cell lines by both suppressing IGF-1-induced IGF-1R activation and reducing IGF-1R protein stability." (PMID 24438088, 2014). "We also observed that the IGF-1R AS sensitized cancer cell lines to cisplatin in vitro through the PI3K pathway." (PMID 24103397, 2013). "IGF1R has been reported to aid in metastasis by allowing the cancer cells to adapt to anchorage-independent growth." (PMID 24244833, 2013). "Binding of ganitumab inhibited the high-affinity interaction of IGF-1 and IGF-2 required to activate IGF1R in cells engineered for IGF1R hypersensitivity and in human cancer cell lines, resulting in complete blockade of ligand-induced cellular proliferation." (PMID 23383308, 2013). "The IGF-1R signaling pathway plays an important role in the formation and progression of human cancers and has been targeted for cancer treatment." (PMID 24182354, 2013). "After incubating cancer cells with IGF-IR AS for 48 hrs in SFM, IGF-1R expression was effectively inhibited by at 30-50 ng/ml IGF-1R mRNA oligonucleotides." (PMID 24103397, 2013). "High IGF-1 plasma concentrations and the presence of IGF-1R on the cell surface are found in many cancers, but in the case of EC, the role of circulating IGF-1 is controversial." (PMID 24308813, 2013). "EGFR and IGF-1R are commonly overexpressed in a significant number of cancers, included breast cancer, and its overexpression have been implicated to influence the response to irradiation in breast cancer cells." (PMID 23777562, 2013). "A lower expression of Bcl-2 and a higher expression of IGF-1R in unclassified tumors compared to ER/PR + HER2- were thus suggested to be partly involved in the reported worse prognosis of unclassified type cancer than ER/PR + HER2-." (PMID 24245483, 2013). "IGF-1 and IGF-1R both have been shown to be upregulated in multiple cancer cell types, affecting proliferation, differentiation, and metastasis." (PMID 24103397, 2013). "In the past decades, a large body of evidence has arisen, supporting a key role for IGF-1R signaling in various types of human cancers." (PMID 23525758, 2013). "We are only beginning to understand the mechanisms by which cancers are resistant to IGF-1R targeted agents." (PMID 23383402, 2013). "In this mini review, I will discuss the role of the IGF signaling system in human cancer and the main strategies which have been so far evaluated to target the IGF-1R." (PMID 23525758, 2013). "Currently, clinical trials of IGF-1R antibodies and kinase inhibitors are ongoing in treating various human cancers." (PMID 24182354, 2013).
cancer (continued). "In contrast to the other investigated markers, the pooled prevalence of IGF1R was lower in grade III versus grade I cancers (41% versus 57%, p < 0.001), and was lower in T3 cancers compared to T1 cancers (39% versus 45%, p = 0.047)." (PMID 24206539, 2013). "It has to be noted that besides HER2-imaging agents, there are currently several new Affibody molecules targeting other cancer-associated receptors, e.g. EGFR, IGF-1R, PDGF-Rβ and HER3, under development." (PMID 23936372, 2013). "miR-431 was upregulated by the addition of human fibroblast interferon (HuIFN-β) in a non-cancer HuIFN-β sensitive cell line RSa, with concomitant suppression of IGF1R signaling and reduction of cell viability." (PMID 24167472, 2013). "Because of the over-representation of IGF1R signaling, and because of its known role in cancer, we decided to study expression of members of this pathway in detail." (PMID 23688189, 2013). "Understanding the specific mechanistic functions of IGF1R with respect to determining the PKA survival functions would have potential for impact upon the development of new therapeutic strategies by exploiting the IGF1R/cAMP-PKA survival signaling in cancer." (PMID 24083380, 2013). "The sorted IGF-1R-expressing cells displayed features of cancer stem/progenitors such as mammosphere formation in vitro and tumorigenicity in vivo, both of which were suppressed by knockdown of IGF-1R." (PMID 23663564, 2013). "For BC0145 xenograft, the identification of cancer stem/progenitors based on IGF-1R expression (one out of 54,785) was slightly better than ALDH+ (one out of 93,412) but not as good as CD24-CD44+ (one out of 6,401)." (PMID 23663564, 2013). "The use of IGF-1R inhibitors, mechanisms of resistance, and current ongoing clinical studies using IGF-1R inhibitors in pediatric cancers are reviewed here." (PMID 23383402, 2013). "The addition of AS against the IGF-1R mRNA decreased cancer cell growth rate by 70%, both in the presence and absence of exogenous IGF-1 (P < 0.05)." (PMID 24103397, 2013). "The preclinical data in pediatric cancers, mechanisms of resistance, and current ongoing clinical studies using IGF-1R inhibitors are reviewed here." (PMID 23383402, 2013). "In summary, mechanistic and epidemiological studies have provided substantial information supporting a role for IGF signaling and the IGF-1R in human cancers." (PMID 23525758, 2013). "The identification of predictive biomarkers is of crucial importance for the further development of anti-cancer therapies based on anti-IGF-1R agents." (PMID 23525758, 2013). "For instance, upregulation of insulin-like growth factor receptor (IGF1R), seen in subnetwork 3, has been identified in a wide variety of human cancers, and in vitro evidence suggests that this upregulation contributes to resistance against EGFR inhibitors." (PMID 24068912, 2013). "The results showed that IGF-1R proteins were expressed in the carcinoma tumors at much higher levels than in the matched normal tissue." (PMID 24182354, 2013). "Of the three translational approaches to IGF-1R-targeted cancer therapy, anti-receptor antibodies and receptor tyrosine kinase inhibitors are in advanced development at various stages, and anti-ligand antibodies are rapidly gaining in interest." (PMID 22952934, 2012). "As a first step, we assessed the anti-proliferative effect of figitumumab, a monoclonal antibody that prevents ligands from binding to IGF1R, on 17 cancer cell lines." (PMID 22438913, 2012). "In cancer cells with high levels of IGF1R/IR HRs, IGF1 and IGF2 activate various downstream signaling pathways through heterodimeric receptors rather than through homodimeric IGF1Rs." (PMID 22438913, 2012). "A variety of reagents have been developed to modulate IGF signaling activities including monoclonal antibodies against IGFs and receptor IGF1R, as well as associated RTK inhibitors in aim for cancer treatment." (PMID 23152806, 2012).
cancer (continued). "Active Src can also activate Akt, and both Src and Akt up-regulate IGF-1R expression in this cancer." (PMID 23006971, 2012). "Hex-hR1 and hR1 are generally comparable in their bioactivities under the conditions investigated, although Hex-hR1 did show a higher potency than hR1 in downregulating IGF-1R and in inhibiting proliferation of certain responsive cancer cell lines." (PMID 22952934, 2012). "The insulin-like growth factor I receptor (IGF1R) is overexpressed in several forms of human cancer, and it has emerged as an important target for anticancer drug design." (PMID 22778948, 2012). "In other words, overexpression of IR serves as a major mechanism of IGF1R signaling in cancer cells by enabling the formation of more heterodimers which are available for binding ligands including IGF1, IGF2, and insulin." (PMID 22438913, 2012). "Regarding specific pathways, insulin-like growth factors (IGFs) are commonly upregulated in cancers and activate IGF1R, which subsequently activates the pro-tumourigenic PI3K-Akt pathway." (PMID 22880013, 2012). "Insulin-like growth factor-1 receptor (IGF-1R) is a transmembrane tyrosine kinase receptor commonly overexpressed in many cancers." (PMID 22931894, 2012). "Insulin-like growth factor 1 receptor (IGF1R) has been examined as a potential therapeutic target for various cancers." (PMID 22438913, 2012). "Insulin-like growth factor 1 receptor (IGF1R) is an attractive drug target for cancer therapy and research on IGF1R inhibitors has had success in clinical trials." (PMID 23242155, 2012). "Several studies have demonstrated increased expression of the IGF-1R in different cancers, where it facilitates anchorage-independent growth, migration and chemoresistance." (PMID 22159423, 2012). "Accumulated evidence during the last decades indicate a pivotal role for the IGF-1R signaling in cancer cells, suggesting this receptor to be a promising molecular target in cancer treatment." (PMID 22159423, 2012). "Increased expression and activation of the IGF1R and its downstream signaling targets are related to human cancers." (PMID 22693602, 2012). "Over-expression of the insulin receptor (InsR) and of the closely related IGF1 receptor (IGF1R) is critical for insulin/IGF system over-activation in cancer." (PMID 22558377, 2012). "IGF-1R has an important role in anchorage independent growth of cells, leading to metastasis of cancer." (PMID 22792362, 2012). "Both IGF-1R and INSR are found over-expressed in a variety of human cancer types and are associated with malignant tumor progression." (PMID 22879999, 2012). "Combinatorial targeting of receptor tyrosine kinases (such as the IGF-1R) and their downstream signaling mediators is a very promising approach to develop more efficient anti-cancer therapies." (PMID 23056595, 2012). "IGF-1R is regarded as a mediator for cancer cell proliferation, differentiation, growth and progression." (PMID 22720981, 2012). "A number of therapeutic approaches are currently being explored to interfere with IGF1R signaling in cancer cells, including RNA interference, receptor antibodies, and small molecule kinase inhibitors." (PMID 22778948, 2012). "Although IGF-1R axis components can be highly altered in cancer, little is known about molecular mechanisms involved in this process." (PMID 22415797, 2012). "As a result, several studies have revealed the increased effectiveness of targeting heterodimeric receptors or simultaneously targeting both the IGF1R and IR as novel anti-cancer therapies compared to targeting IGF1Rs alone." (PMID 22438913, 2012). "IGF1R is also often overexpressed at the cell surface of malignant cells and thus has emerged as an attractive therapeutic target in cancer." (PMID 21197471, 2011). "Mounting evidence has also demonstrated a crucial role of IGF1R signaling in the development and progression of cancer." (PMID 22091383, 2011).
cancer (continued). "Following a necessarily brief summary of the IGF-1R family and its cancer promoting effects, the crux of this review has been dedicated to mechanisms of IGF-1R resistance and dual-targeted strategies aimed at circumventing them." (PMID 24212944, 2011). "Then the amplification of IGF-1R gene and overexpression of its protein product closely relate to the poor prognosis in cancer patients." (PMID 22072919, 2011). "Over expression of IGF-II is reported in multiple types of cancer and is proposed as a potential mechanism for cancer cells to develop resistance to IGF-1R-targeting therapy." (PMID 21859454, 2011). "In contrast, most compounds targeting the mTOR and IGF1R pathways equally inhibited both invasive and non-invasive spheroids, normal cells in 3D, or cancer cells in monolayer cultures." (PMID 20454659, 2010). "Reports from clinical trials give reason for optimism regarding the use of IGF1R inhibitors in cancer patients." (PMID 20924377, 2010). "IGF1R has been found to be both significantly overexpressed and highly activated in cancer cells with respect to its status in normal breast tissue." (PMID 20550684, 2010). "Given the critical role of IGF1R in cancer biology, many new anti-IGF1R drugs have been developed, including monoclonal antibodies and tyrosine kinase inhibitors." (PMID 19491901, 2009). "The type I insulin-like growth factor receptor (IGF1R) is a receptor tyrosine kinase that plays critical roles in cancer progression and metastasis." (PMID 19491901, 2009). "A variety of strategies to target IGF-1R in cancers are now in preclinical or clinical stages of development." (PMID 19806209, 2009). "In IGF-I-driven cancers, it is highly probable that the cancer-specific effects of IGF1R activation are mediated in part through the activation of cap-mediated translation." (PMID 19603014, 2009). "The IGF receptor type 1 (IGF-1R) pathway is frequently deregulated in human tumors and has become a target of interest for anti-cancer therapy." (PMID 19806209, 2009). "The type I insulin-like growth factor receptor (IGF1R) is a transmembrane tyrosine kinase involved in cancer proliferation, survival, and metastasis." (PMID 19491901, 2009). "The IGF-1R pathway appears to play important roles in tumorigenesis, metastasis, and resistance to existing forms of anti-cancer therapy." (PMID 19806209, 2009). "The IGF signalling pathway is activated in various cancers, and monoclonal antibodies targeting IGF1R have been recently developed; IGF1R is a transmembrane tyrosine kinase receptor, and both IGF1 and IGF2 are ligands for IGF1R." (PMID 19034281, 2008). "Induction of c-Myc expression by IGF-1R activity can increase resistance to apoptosis in cancer cells." (PMID 19784388, 2008). "The functional interaction of these proteins in cancer is further demonstrated by the known role that IGF-1R plays in development of resistance to EGF-R inhibitors." (PMID 19784388, 2008). "In the past few years, the insulin-like growth factor 1 receptor (IGF-1R) has emerged as a receptor tyrosine kinase (RTK) with important roles in cancer biology." (PMID 17406664, 2007). "Another member of the type II RTK family however, is the insulin receptor (InsR) which shows a high degree of homology with the IGF-1R and has been reported to play a role in cancer development and progression." (PMID 16819546, 2006). "The insulin-like growth factor 1 receptor (IGF-1R) is an important signaling molecule in cancer cells." (PMID 16001973, 2005). "Forthcoming clinical trials are welcome and will indeed be the only way to evaluate the impact of IGF-1R targeting in human cancer." (PMID 15956962, 2005). "The vast expression of IGF-1R in neoplastic cells and tissues combined with its crucial roles in cancer cell growth is making this tyrosine receptor an attractive target to combat malignant diseases." (PMID 15956962, 2005).
cancer (continued). "In many cancers, IGF-1R signalling leads to activation of PI-3 K and MAPK pathways, stimulates proliferation, promotes angiogenesis and metastasis, and inhibits apoptosis." (PMID 15150607, 2004). "IGF-II is a potent mitogen with essential roles in fetal development; in adult tissues, its expression is typically restrained but is frequently reactivated in cancer, where it can sustain signaling through IGF-1R and the IR isoform A (IR-A) to support proliferation and survival." (PMID 41511360, 2026). "Moreover, the enzyme inhibition of IGF-1R by tyrosine kinases increases the antitumor immunity of cancer cells, which is required for the induction of autophagy." (PMID 39942843, 2025). "Overexpression of IGF1R in cancer enhances cell survival and proliferation, and inhibits apoptosis." (PMID 39950029, 2025). "Furthermore, it has been suggested that IGF1R upregulation is an early event in hepatocarcinogenesis, where it maintains high proliferation and cancer stemness in transformed hepatocytes." (PMID 40115165, 2025). "Similarly, in a model of pancreatic ductal adenocarcinoma, the IGF-1R tyrosine kinase inhibitor linsitinib was employed to target and eliminate residual cancer cells that had persistently survived despite the ablation of key oncogenes such as c-MYC or K-RAS." (PMID 41404065, 2025). "In addition, since IR-A and IGF1R have overlapping and complementary downstream effects in cancer, co-targeting both has been proposed as a potential therapeutic strategy." (PMID 40303997, 2025). "Furthermore, bypass signaling activation via IGF1R is recognized as a mechanism of resistance to mTKIs across multiple cancer types." (PMID 41275311, 2025). "To evaluate whether oHSV treatment sensitizes cancer cells to IGF1R inhibition, we used OSI-906, a potent orally available small-molecule IGF1R inhibitor." (PMID 41510300, 2025). "Interestingly, increasing the clearance of extracellular IGF-II by the treatment with these Man-6-P multivalent molecules inhibited the proliferation of several cancer cell lines due to a decreased IGF1R activation." (PMID 40332073, 2025). "By promoting cytoskeletal rearrangements, cell motility, and extracellular matrix degradation, IGF-1R signaling may facilitate the invasion of cancer cells into lymphatic vessels and subsequent dissemination to regional lymph nodes." (PMID 39328205, 2024). "Furthermore, much work has focused on the role of IGF1R activity in tumorigenesis with a view to developing IGF1R inhibitors for therapeutic use in cancer that attenuate the deleterious mitogenic effects of IGF signaling." (PMID 38706850, 2024). "In contrast to the results observed after IGF1R abrogation in EpCAMhigh cancer cells, loss of IGF1R signaling in EpCAMlow cancer cells did not affect the ability of these hybrid cancer cells to generate mesenchymal cSCCs." (PMID 39075581, 2024). "Inhibiting PRKCSH could revitalize the immune response, enhancing NK cell-based cancer therapy by disrupting IGF1R stability and activation, thus overcoming TNFSF resistance." (PMID 38571496, 2024). "The activation of IR as well as IGF-1R/IR hybrid receptors by insulin may contribute to cancer growth, leading to resistance to IGF-1R inhibition." (PMID 39335147, 2024). "Moreover, loss of ITGB1 protein expression in actively adhering migratory cancer cells promotes IGF-1R retention at the plasma membrane, impairing its internalization and intracellular trafficking." (PMID 39608716, 2024). "Additionally, miR-598-3p can directly targets RMP and IGF1r, the key regulators of glucose metabolism and relevant malignant phenotypes of cancer cells." (PMID 38491378, 2024).